ESR1 (estrogen receptor 1)
Diseases named in the same sentence as ESR1 in open-access papers (continued):
Sharing a sentence is not in itself a finding about the gene and the disease.
breast cancer (continued). "A PDX harboring ESR1-Y537S, WHIM20, has been generated from a patient with endocrine-refractory metastatic ER+ breast cancer that retains genomic features of the human counterpart." (PMID 31106278, 2019). "The present study indicated another type of crosstalk in which ESR1 and FOXO3 interact and are co-upregulated in the nucleus of LTED cells, which serve as a model for endocrine therapy-resistant breast cancer." (PMID 31439835, 2019). "There is only a weak, positive correlation between ESR1 and GRHL2 expression in the TCGA and METABRIC breast cancer datasets." (PMID 31084623, 2019). "However, in a recent investigation, our group could not confirm a relationship between ESR1 genetic profile and the risk of development of mammary tumors." (PMID 31506083, 2019). "Those genes near essential FOXA1 binding sites are enriched in breast cancer-related functions and pathways, including metaplastic/ductal carcinoma of the breast, luminal breast cancer, hypoxia response in MCF7 cells, and targets of ESR1." (PMID 31727847, 2019). "Therefore, we assume that studying the effects of early parity on some genes such as ESR1 and FOXA1, which have important functions in estrogen responsiveness, can improve the better understanding of underlying mechanisms of early pregnancy associated with breast cancer protective effect." (PMID 30054444, 2019). "Notably, ESR1 has been identified as a driver gene of cancer metastasis and associated mutations can cause endocrine resistance of metastatic breast cancer cells, yet none of the cell lines could be used to appropriately model it." (PMID 31092827, 2019). "CDKN1A is p21, validating the approach, and ESR1 is estrogen receptor alpha, likely reflecting our use of ER+ MCF7 human mammary carcinoma cells." (PMID 30987592, 2019). "Analysis of different data sets of breast cancer patients showed that MYC overexpression anti-correlated with ESR1 and GATA3 transcript levels." (PMID 29523784, 2018). "Accordingly, the expression levels of ESR1 and LRIG1 were correlated in breast cancer (Spearman's correlation coefficient, 0.56), other cancers, and many normal tissues." (PMID 29317492, 2018). "To establish the pathological relevance of the anti-correlation between MYC overexpression and ESR1/GATA3 downregulation, we assessed the expression level of these ML-specific TFs in large cohorts of breast cancer samples." (PMID 29523784, 2018). "Targeted therapy for breast cancer (as well as other cancers) is directed towards overly expressed cellular receptors such as HER2, and ESR1." (PMID 30373175, 2018). "Previous studies in endometriosis and breast cancer reported that GREB1 is mainly nuclear, which supports its role as an ESR1 cofactor." (PMID 29973689, 2018). "Next, we investigated how the estrogen receptor 1 (ESR1) agonist estradiol and the selective estrogen receptor modulators (SERMs) raloxifene and GW7604 affect proteostasis in MCF-7 breast cancer cells." (PMID 29551266, 2018). "We found that breast cancer subtypes could be assigned with >90% diagnostic accuracy, as indicated by the area under the ROC curve of the partition tree, by differential expression analysis with respect to a normal breast tissue reference using only 4 genes: CBX7, ESR1, FOXC1, and FOXM1." (PMID 29868123, 2018). "ESR1 and PGR-positive breast cancers make up the Luminal A (Ki-67-negative) and Luminal B (Ki-67-positive) subtypes." (PMID 30279965, 2018). "We first aimed to stratify the RNA-Seq data available from The Cancer Genome Atlas according to the three major breast cancer subtypes: HER2-positive, ESR1/PGR-positive, and triple negative." (PMID 30279965, 2018). "Based on these thresholds, the assay can be used for the robust quantification of ERBB2, ESR1, PGR and MKI67 on whole sections of FFPE samples during routine histopathological work-up of breast carcinoma." (PMID 30342538, 2018).
breast cancer (continued). "Previously, we reported that higher NR2E3 levels are strongly associated with good clinical outcomes in breast cancer by maintaining the expression of estrogen receptor α (ESR1), a major guideline for breast cancer prognosis and treatment." (PMID 28878246, 2017). "Our analysis validates ESR1 function as a main regulator linking cancer-related TFs, especially GATA3 to promote breast cancer development." (PMID 29051499, 2017). "But, a very recent study shows a higher serum level of endogenous estrogen (E2) and estrogen receptors (ESR1, ESR2) in breast cancer patients with worse prognosis." (PMID 28479926, 2017). "The identified E2-responsible TRNs provide evidence that ESR1 form modulators with co-TFs or cofactors to regulate the downstream genes, especially with GATA3 to promote E2-inducd gene expression programs in breast cancer." (PMID 29051499, 2017). "Twenty-three candidate SNPs which are separately distributed in six genes, namely, COMT, CYP19A1, ESR1, PGR, SHBG, and STS are involved in the progress of breast cancer." (PMID 28143579, 2017). "Our findings highlight the feasibility of using RT-qPCR for the routine assessment of ESR1, PGR & MKI67 in order to assist the selection of breast cancer patients for neoadjuvant treatment." (PMID 28193205, 2017). "The specific highest IRS in MCF7 (breast cancer, BRCA), HL60 (acute promyelocytic leukemia, APL), and PC3 (prostate cancer, PRAD) cells was achieved by fulvestrant (ESR1 antagonist), tretinoin (all-trans retinoic acid), and pioglitazone, respectively." (PMID 29023443, 2017). "In an inferred TRN, ESR1 interacts with other TFs such as AP1, GATA3, and CEBP to mediate distinct biological functions in breast cancer cells." (PMID 29051499, 2017). "Until now only estrogen receptor (ESR1) and progesterone receptor (PGR) have been routinely assessed as hormone receptors in human breast cancer due to their prognostic and predictive value in human mammary carcinoma therapy." (PMID 27649560, 2016). "ESR1 has the highest correlation coefficient r−0.89 in 173 TCGA tumors, and r = 0.68 in 29 CCLE cell lines of breast cancer between mRNA and protein." (PMID 27556158, 2016). "This subtype (luminal, ESR1+, PGR+) represents 40-75% of newly diagnosed breast cancers and responds well to hormone therapy." (PMID 26783963, 2016). "Herein, the ESR1, PGR, PRLR and GHR gene expression were analyzed and the results showed all hormone receptors to be significantly lower expressed in malignant mammary tumors compared to the group of reference tissue and benign tumors." (PMID 27649560, 2016). "From a technical perspective applying RT-qPCR for resolving the status of ERBB2, ESR1, PGR, and MKI67 represents an efficient and reproducible alternative for decentralized routine assessment of breast cancer molecular subtypes." (PMID 27389414, 2016). "Breast cancers with high levels of CACNA1H (Cav3.2) (2nd, 3rd, 4th quartile) showed a significant elevation in levels of ESR1 and PGR compared to breast cancers with significantly low levels of Cav3.2 (1st quartile)." (PMID 27034617, 2016).
breast cancer (continued). "Median of normalized gene expression of ESR1 and PGR in intact (fresh frozen n = 57; FFPE n = 83) and neutered (fresh frozen n = 11; FFPE n = 8) females with malignant mammary tumors." (PMID 27649560, 2016). "Some genes, well-known in breast cancer subtyping and involved in the cancer-relevant pathways, are the hubs of the network, e.g., FOXQ1, SFRP1 and ESR1." (PMID 27786176, 2016). "Estrogen receptor alpha/estrogen receptor 1 (ERα/ESR1) is a nuclear hormone receptor and oncoprotein that is expressed in approximately 70% of breast cancers." (PMID 26909605, 2016). "For a panel of 38 breast cancer cell lines, we identified a significant number of surrogate oncogenes in known oncogenes such as BRCA1 and ESR1, lending credence to this approach." (PMID 26779250, 2015). "The most common breast cancer subtype, which comprises over 70% of all breast cancers, expresses the estrogen receptor-α (ESR1; ERα)." (PMID 26157705, 2015). "The estrogen receptor gene (ESR1) appears among the top ranked genes in both analyses, confirming the extensive evidence in the literature that breast cancers classified on the basis of expression levels of this gene have distinctive etiologies." (PMID 25974664, 2015). "The most striking subtype distinction in breast cancer is provided by expression of ESR1, the estrogen receptor (ER)." (PMID 26717410, 2015). "This was done for two human TFs, ESR1 and SPIB in breast cancer and diffuse large B cell lymphoma, respectively." (PMID 26099425, 2015). "We also examined two gene regions (ESR1 and GSTM2) found to display hypermethylation preferentially in more aggressive breast cancers." (PMID 26510686, 2015). "Of interest, 'A' genes show the strongest expression in the breast cancer cell line MCF7 and the highest ESR1 ChIP-seq tag density." (PMID 26099425, 2015). "Gene expression of ERα (ESR1), PGR, PRLR, GHR and CDH-1 was detected in normal mammary tissues and in all mammary neoplasms, except in one carcinoma." (PMID 26370564, 2015). "Analysing ESR1 and SPIB in breast carcinoma and activated B cell-like diffuse large B-cell lymphoma cell lines, respectively, revealed that the concerted binding to high and low affinity sites correlates best with gene expression." (PMID 26099425, 2015). "Furthermore, the retained sensitivity but decreased efficacy of anti-estrogens in preclinical ESR1 mutant models suggests that the standard dose of anti-estrogens such as tamoxifen often used in the aromatase inhibitor-refractory setting may be inadequate in ESR1 mutant breast cancers." (PMID 25928204, 2014). "For example, we identified the lncRNA RP3-443C4.2 within the vicinity of estrogen receptor 1 (ESR1), a gene with important functions in breast cancer." (PMID 25296969, 2014). "More recently, Wang and colleagues used pyrosequencing to examine gene-specific (p16, RASSF1A, RARβ2, ESR1, LINE1, CDH13, HIN1, and SFRP1) methylation in breast tumor DNA from 32 AA and 33 EA breast cancer patients." (PMID 24368439, 2014). "Inrecent years, studies have been conducted to evaluate the anti-cancer effect of silybin.We studied the effect of silybin and silybin-phosphatidylcholine on ESR1 and ESR2 geneexpression and viability in the T47D breast cancer cell line." (PMID 24611152, 2014). "HMX3 has been shown to integrate ESR1 and HER2 receptor tyrosine kinase signaling to promote aromatase expression and hormone resistance in a preclinical model of luminal breast cancer." (PMID 25183703, 2014). "In the near future simultaneous determination of ESR1 and HER2 status with additional marker genes will most probably be part of multigenic breast cancer classification." (PMID 27605190, 2013). "Expression of the estrogen receptor-α (ERα) gene, ESR1, is a clinical biomarker used to predict therapeutic outcome of breast cancer." (PMID 24339902, 2013).
breast cancer (continued). "First, we perform a large gene expression microarray-based analysis incorporating the measurement of mRNA levels of ESR1 and PGR from approximately 4 K breast cancers." (PMID 23971947, 2013). "Multivariable analyses using the LASSO revealed that expression of PGR, ESR1, NAT1, GABRP, TBC1D9, SLC39A6 and LRBA of the 32 gene candidates was collectively the most important predictors for both breast cancer mortality and recurrence." (PMID 23819905, 2013). "In the case of MGERA, we chose estrogen receptor, ESR1, as the initial starting point, since it is one of the dominant and systemic factor in breast cancer; in the case of TraceRNA, we also chose gene ESR1 and its modulated gene network." (PMID 23573084, 2013). "To gain further insight into the relationship of ESR1 and PGR expression, we performed a scatterplot of ESR1 and PGR mRNA expression levels across 4,111 breast cancers." (PMID 23971947, 2013). "Interestingly, beta-catenin knockdown also hindered the hypoxia-induced down-regulation of ESR1, revealing the capability of beta-catenin to play a pivotal role in the hypoxia-induced de-differentiation program that parallels the gain of stem cell features in breast cancer cells." (PMID 24260469, 2013). "Consistent with its suspected role as an endocrine disruptor, the estrogen-dependent breast cancer signaling pathway was marginally enriched (p-value = 0.043) because three genes (EGFR, ESR1 and CCND1) were used to make the inference." (PMID 23144783, 2012). "ESR1 and GSTP1 promoter hypermethylation seem to be involved in development and/or progression of high-grade male breast cancer." (PMID 22765268, 2012). "Particularly, ESR1, BRCA1 and BRCA2 were less often methylated compared with female breast cancer and were strong independent predictors of gender in logistic regression analysis (P = 0.005, P = 0.010 and P < 0.001, respectively)." (PMID 22765268, 2012). "Both proteins play an important role in breast cancer, where SRC3 serves as the main co-activator of estradiol-dependent ESR1." (PMID 22219718, 2011). "Known therapeutic targets for breast cancer, such as ESR1, ERBB2 (HER2) and ERBB3 (HER3), are identified as showing bimodality in their gene expression level in breast cancer." (PMID 22053771, 2011). "Our previous report shows that Sin3A controls expression of the ERα gene itself, ESR1, and Sin3A can interact with ERα in ERα-positive breast cancer cells." (PMID 20920219, 2010). "This study provides a higher level of evidence that DC-SCRIPT is indeed an independent, pure prognostic, factor for primary breast cancer and shows that DC-SCRIPT mRNA expression is most informative for either ESR1-positive and/or ESR2-low pT1 tumors." (PMID 21122099, 2010). "We took as «baits» five bimodal genes reported as important breast cancer genetic markers - ERBB2, ESR1, PLAUR, FN1, and STAT1, and calculated the "close neighbor" gene groups that were synchronously expressed with each of them in the Sorlie295 set." (PMID 20158879, 2010). "We previously showed that the Sin3A transcriptional repressor protein is a regulator of estrogen-induced repression of the ERα gene, ESR1, in breast cancer cells." (PMID 20920219, 2010). "Our lab previously showed that Sin3A regulated the estrogen-induced repression of the ERα gene, ESR1, in the MCF7 breast cancer cell line." (PMID 20920219, 2010). "In breast cancer, FOG-2 expression is also correlated with favourable prognosis, likely as it is required for the normal expression of its downstream target genes Esr1 and Foxa1." (PMID 19707195, 2009). "In breast cancer, a variety of critical genes have been shown to be silenced by methylation (e.g., BRCA1, 14-3-3, TIM3, ESR1, PGR and E-cadherin)." (PMID 19267929, 2009).
breast cancer (continued). "Variation in the ESR1 (MIM 133430) and EGF (MIM 131530) genes affecting the function or expression of their respective proteins could thus potentially affect the risk of developing breast cancer, characteristics of the tumour or the risk of dying from the disease." (PMID 18271972, 2008). "Several peer-reviewed publications have highlighted the joint regulation of the estrogen receptor-a (ESR1/ER-α), GATA3 and FOXA1 in breast cancer cells." (PMID 19104654, 2008). "We genotyped 157 SNPs in ESR1 and 54 SNPs in EGF using a population-based case-control study, which included 1,590 breast cancer cases and 1,518 controls." (PMID 18271972, 2008). "In breast cancer, a variety of critical genes were shown to be inactivated by methylation e.g. BRCA1, 14-3-3σ, TIM3 ESR1, PGR and E-cadherin." (PMID 18513385, 2008). "The oestrogen receptor alpha (ESR1) transcript, a gene of special significance in breast cancer, was used as a target gene to compare the effect of choice of EC on the estimate of gene quantity." (PMID 18042273, 2007). "An age signature validated against two other independent breast cancer datasets proved to have >80% accuracy in discerning younger from older ER-positive breast cancer cases with characteristic differences in AREG and ESR1 expression." (PMID 17850661, 2007). "A cohort study was conducted to examine the role of genetic polymorphisms in three estrogen metabolizing enzymes (COMT, CYP1A1, CYP1B1) and the two estrogen receptors (ESR1, ESR2) in the progression of benign breast disease (BBD) to breast cancer." (PMID 16808847, 2006). "Recently we performed a cross-platform comparison between SAGE and DNA microarray profiles showing that the ESR1, GATA3, and MUC1 genes are very tightly co-expressed in breast carcinomas." (PMID 17078870, 2006). "Such analysis by bioinformatics showed that there was a correlation between PARP1 and BRCA1/2, and at the same time, with ESR1 in the HER2 subgroup; those breast cancer patients can receive not only PARP inhibitors, but also tamoxifen or other drugs for positive ESR1 patients as therapeutic drugs." (PMID 40141415, 2025). "When adjusted for standard of care (ESCAT I‐II) genes (i.e., PIK3CA, ESR1, and ERBB2 for breast cancer; KRAS, NRAS, and BRAF for colon cancer, etc.), 37 (3.6%), 0 (0%), 1 (0.2%), and 0 (0%) of mutant alleles would have been negative among breast, bowel, lung, and skin cancer samples, respectively." (PMID 40056420, 2025). "Among HER2 + stage I-III breast cancers with early (N = 20) and late (N = 20) recurrence, the most frequent alteration, other than HER2 amplification, was PIK3CA (45% vs 25%), followed by BRCA1/2 (10% vs 5%), ESR1 (0% vs 5%), PD-L1 amplification (5% vs 0%)." (PMID 40421962, 2025). "In hormone receptor-positive tumors, GATA3 modulates cell proliferation through estrogen-responsive genes (e.g., ESR1 and GREB1), while TRPS1 may similarly influence hormonal signaling in breast cancer." (PMID 40969274, 2025). "BPA may also depend on Esr1 and HDAC6 to promote breast cancer and may further lead to the activation of oncogene c-Myc in Osteosarcoma." (PMID 41440754, 2025). "By contrast, ESR1 amplification, which is a known oncogenic event in advanced ER+ breast cancer occurred exclusively in the metastatic setting, whereas ESR1 deletion was notably absent." (PMID 40826108, 2025). "In breast cancer vaccines, commonly used tumor antigens include HER-2, MUC1, ESR1, CA-125, etc." (PMID 40342927, 2025).